SH2B2 (SH2B adaptor protein 2)
Description:
Adapter protein for several members of the tyrosine kinase receptor family. Involved in multiple signaling pathways. May be involved in coupling from immunoreceptor to Ras signaling. Acts as a negative regulator of cytokine signaling in collaboration with CBL. Binds to EPOR and suppresses EPO-induced STAT5 activation, possibly through a masking effect on STAT5 docking sites in EPOR. Suppresses PDGF-induced mitogenesis. May induce cytoskeletal reorganization via interaction with VAV3.
Synonyms: APS
Tractability: Antibody: UniProt places it where antibodies can reach, with high confidence; its Gene Ontology location is reachable by antibodies, with high confidence. PROTAC: ubiquitination databases record sites on it; its protein half-life has been measured.
Gene: Protein-coding gene on chromosome 7 (102,284,995 to 102,321,712, forward strand). Ensembl gene ENSG00000160999.
Subcellular location: Cytoplasm; Cell membrane
Subcellular location (Human Protein Atlas): Cytosol
Pathways (Reactome):
Hemostasis: Factors involved in megakaryocyte development and platelet production
Signal Transduction: Regulation of KIT signaling
Gene Ontology:
Molecular function: protein binding; SH2 domain binding; signaling adaptor activity; transmembrane receptor protein tyrosine kinase adaptor activity
Biological process: B cell receptor signaling pathway; insulin receptor signaling pathway; intracellular signal transduction; signal transduction
Cellular component: cytoplasm; plasma membrane; cytosol; actin filament; ruffle; stress fiber
Genetic constraint (gnomAD): Loss-of-function variants: 40 observed, 29.13 expected, observed/expected ratio (o/e) 1.37, 90% interval 1.07 to 1.77. The synonymous counts are far from expectation, so gnomAD's model fits this gene poorly and the ratio says little. Missense variants: 852 observed, 614.75 expected, observed/expected ratio (o/e) 1.39, 90% interval 1.31 to 1.47. Synonymous variants: 383 observed, 278.33 expected, observed/expected ratio (o/e) 1.38, 90% interval 1.26 to 1.5.
Homologues: Orthologues: chimpanzee SH2B2 (99% identical), macaque SH2B2 (96% identical), pig SH2B2 (89% identical), dog SH2B2 (88% identical), guinea pig SH2B2 (87% identical), rabbit SH2B2 (85% identical), rat Sh2b2 (83% identical), mouse Sh2b2 (83% identical), tropical clawed frog sh2b2 (61% identical), zebrafish SH2B2 (56% identical), Drosophila melanogaster Lnk (27% identical). Paralogues in human: SH2B1 (43% identical), SH2B3 (31% identical).
Diseases named in the same sentence as SH2B2 in open-access papers:
SH2B2 is named in the same sentence as 19 diseases in open-access papers, as found by Europe PMC text mining. Sharing a sentence is not in itself a finding about the gene and the disease. The quoted sentences say what the papers report.
Insulin resistance (2 papers, 2013 to 2023). Increased resistance towards insulin, that is, diminished effectiveness of insulin in reducing blood glucose levels. "Furthermore, simultaneous deletion of both hepatic SH2B1 and whole body SH2B2 neither caused insulin resistance nor exacerbated HFD-induced insulin resistance and glucose intolerance." (PMID 24358267, 2013). "Adult-onset deletion of SH2B1 in the liver either alone or in combination with whole body SH2B2 knockout also did not exacerbate HFD-induced insulin resistance and glucose intolerance." (PMID 24358267, 2013).
Burkitt lymphoma (1 paper, 2025). A rare form of malignant mature B-cell non-Hodgkin lymphoma. "Additionally, in Burkitt’s lymphoma cell lines, SH2B2 is phosphorylated on tyrosine upon B-cell receptor stimulation." (PMID 40149878, 2025).
cognitive (1 paper, 2025). "Impaired SH2B2 function (e.g., rs2023482‐T) elevates UF OD values, reflecting axonal disorganization and conduction delays—a possible substrate for cognitive–emotional deficits associated with smoking." (PMID 41289983, 2025).
colon adenocarcinoma (1 paper, 2025). "The immunologic significance of SH2B2 is related to the invasion of colon adenocarcinoma." (PMID 41140666, 2025).
depression (1 paper, 2025). "Additionally, our study identifies the left UF and SH2B2 as central players in the causal effect of smoking on depression, offering a genetic framework that elucidates the cyclical interplay among polygenic risk, white matter disruption and corticolimbic dysregulation." (PMID 41289983, 2025).
Hepatic steatosis (1 paper, 2013). Steatosis is a term used to denote lipid accumulation within hepatocytes. "Adult-onset deletion of liver SH2B1 similarly attenuated HFD-induced hepatic steatosis in SH2B2 KO mice 29 days after infection." (PMID 24358267, 2013).
Hypertension (1 paper, 2021). The presence of chronic increased pressure in the systemic arterial system. "From the DO analysis, the following potential gene targets have been selected, these include CLCNKB, CYPB11B2, SH2B2, STK9, and TBX5 as they show interactions exclusively with hypertension-related pathways." (PMID 33917487, 2021).
Hypoinsulinemia (1 paper, 2010). A decreased concentration of insulin in the blood. "In the case of SH2B2, it was reported that SH2B2 null mice develop hypoinsulinemia and show increased insulin sensitivity at young ages." (PMID 20333234, 2010).
lung carcinoma (1 paper, 2022). "We then studied the function of SH2B2/SHP2 interaction in lung cancer." (PMID 35589677, 2022).
Obesity (1 paper, 2020). Accumulation of substantial excess body fat. "This genetic variant, which is a member of the SH2B family of adapter proteins that also include SH2B2 and SH2B3 has been reported to be pathogenic for obesity." (PMID 32365683, 2020).
postpartum hemorrhage (1 paper, 2022). Hemorrhage defined as a blood loss in excess of 500 mL after vaginal delivery or more than 1000 mL after a cesarean delivery. "Eight genes were associated with hemostatic pathways (SELL, CAPZB, SLC16A3, PDPN, TNFRSF10B, SH2B2, NFE2, and TNFRSF10D), which provided novel insights for the prevention and management of postpartum hemorrhage." (PMID 35836580, 2022).
tumor (1 paper, 2021). "Results showed significant upregulated expression of certain genes like Hgf, Hmga1, Rasgrp1, Sh2b2, Socs1, Socs2, and Socs3 in WT mice tumor compared to its ChREBP systemic knockout tumor." (PMID 34685767, 2021).
SH2B2 also shares sentences with these, for which no sentence is quoted: diabetes (1 paper); Glucose intolerance (1); infection (1); periodontitis (1); preeclampsia (1); psychiatric disorder (1); type II diabetes (1).